IL6 (interleukin 6)
Diseases named in the same sentence as IL6 in open-access papers (continued):
Sharing a sentence is not in itself a finding about the gene and the disease.
tumor (continued). "Activating mutations in oncogenic RAS/BRAF/MEK pathways trigger a tumor-intrinsic inflammatory network with the concerted regulation of master transcription factors (TFs) including STAT3, NF-κB and AP-1 which in turn trigger the expression of cytokines, including IL-6, IL-1, IL-10, TNF and VEGF." (PMID 31766350, 2019). "Th2 cytokines such as IL-6 and IL-10 enhance motility and survival of highly tumorigenic cancer stem cells and thus metastasis, while IL-8 is involved in the regulation of angiogenesis, cancer cell growth and survival, tumor cell motion, leukocyte infiltration, and modification of immune responses." (PMID 31448052, 2019). "Additionally, targeting IL-6 in combination with EGFR inhibitors such as Cituximab is currently being investigated as a potential therapy for HNSCC due to the resistance to EGFR inhibition seen in many tumours." (PMID 31226168, 2019). "Importantly, apigenin significantly inhibited the level of IL-6 in the xenograft tumor tissues." (PMID 31572184, 2019). "While IL-6 has been involved in the inhibition of DC differentiation, decreasing the stimulatory effect of DCs on T cells, the secretion of IL-6 by MSCs has been shown to promote anti-tumor adaptive immunity by increasing T lymphocyte trafficking in the tumor microenvironment." (PMID 31709192, 2019). "In addition, STAT3 signaling has been found to regulate both innate and adaptive immunity by increasing the expressions of growth factors and cytokines including TGF-β, VEGF, interleukin 6 (IL-6), and IL-10, which collectively repress the host immune response and facilitate tumor immune evasion." (PMID 30046565, 2018). "Similarly, other authors have shown that ICAM-1 expression in mesothelial cells was increased by pre-incubation with TNF-α or IL-6, with a concurrent increase in tumour adhesion, which was then partially attenuated by the use of a monoclonal antibody against ICAM-1." (PMID 29772648, 2018). "Seven parameterclasses may constitute a reasonable initial framework for building the so-named“Cancer immunogram”, including the evaluation of tumor mutation load,lymphocyte count, intratumoral T cells, PD-L1 expression on tumor, serum levels ofc-reactive protein (CRP), LDH and IL-6." (PMID 29552325, 2018). "Given the extensive tumor-promoting functions reported for both IL-6 and IL-8, dysfunction of the TLR4 signaling pathway which thereafter leads to reduced secretion of IL-6 and IL-8, could contribute to a better tumor prognosis, as seen in patients with HPV+ OPSCC." (PMID 29416610, 2018). "Moreover, S1PR1 was shown to be closely associated with persistent activation of signal transducer and activator of transcription-3 (STAT3) and IL-6 expression in both tumor cells and the tumor microenvironment, both of which contributed to tumor malignant progression and distant dissemination." (PMID 30242145, 2018). "Besides tumour‐derived IL6, IL6 produced by the host adipose tissue may also, at least in part, contribute to the observed systemic increase in IL6 level." (PMID 29540470, 2018). "Thus, elevated serum levels of IL-6 in our cohort of patients might reflect a subgroup of patients with a more aggressive hepatic tumor or tumor microenvironment that is less likely to respond to TACE therapy due to increased tumor regeneration capabilities." (PMID 29899223, 2018). "In addition, CAFs promoted tumor development by angiogenesis through secreting IL-6 and IL-8." (PMID 30591064, 2018). "Thus IL6 stimulation has been linked with defective pericyte coverage and our findings show that both lower levels of pericyte coverage in the tumour vasculature and lower systemic IL6 levels are biomarkers for predicting enhanced survival following treatment with bevacizumab." (PMID 29535825, 2018). "However, a significant association between IL-6 (total expression in tumour and stroma) and negative LN status has recently been reported and such results support IL-6’s association with good prognostic markers in BC." (PMID 29256156, 2018).
tumor (continued). "Therefore, a higher level of IL‐6 is favorable for accumulation of CD8+ T cells in tumor." (PMID 29938166, 2018). "Neutrophils could be stimulated to proliferate by cancer-related inflammatory factors, such as Tumor necrosis factor-alpha and Interleukin-6, which subsequently secrete reactive oxygen species and pro-angiogenic factors, and therefore favors tumorigenesis and tumor microenvironment." (PMID 29940884, 2018). "When normal blood monocytes were incubated with tumor ascites, elevated levels of B7-H4 was observed, whereas, the serum-free medium showed no such effect, thereby suggesting that B7-H4 expression is regulated by the tumor microenvironment, specifically IL-6 and IL-7." (PMID 30274280, 2018). "IL-6 has been suggested as treatment in combination with immunotherapy such as immune checkpoint therapies, cancer peptide vaccines or immunological adjuvants, since IL-6 seems to downregulate the tumor-suppressing tumor micro-environment and has been tested with promising results in murine studies." (PMID 30038723, 2018). "Upregulation of IL-6 could be beneficial for tumor progression and bone metastasis." (PMID 30013512, 2018). "Administration of an anti-IL-6 antibody was able to counteract this increased IL-6 level, leading to an almost complete maintenance of body weight and food intake and preventing the induction of markers of muscle atrophy, despite a slight increase in tumor mass." (PMID 29719601, 2018). "Moreover, IL-6 and CCL2 induce tumor-associated macrophage polarization." (PMID 29867925, 2018). "As we understand more about the role of the immune system in cancer and the ability for tumor cells to block the immune response, researchers and clinicians may be able to design anti-IL-6 clinical trials using patient populations that are identified to have a positive response to these therapies." (PMID 30671025, 2018). "Interestingly, a significant increase in the serum concentrations of TNF and IL-6 was found in the P2Et/P2Et groups compared with the other groups in both tumor models, while in the P2Et/P2Et-treated B16 tumors, the serum concentrations of both IL-17 and IL-4 were significantly decreased." (PMID 30234017, 2018). "In addition, CAFs promote tumor development by secreting IL-6 and IL-8." (PMID 29335551, 2018). "In addition, IL-6 and TNF-α are conductor cytokines that mediate and have multiple physiological functions in various pathogenic inflammatory diseases, where they are involved in tumor progression, angiogenesis, and migration." (PMID 30034291, 2018). "Indeed, IL-6 has been reported to contribute to the onset of castration-resistant PCa by activating alternative pathways involved in cancer survival and proliferation and by inducing androgen receptor overexpression in tumor cells." (PMID 29896191, 2018). "Because IL-6 can activate the NF-κB pathway to express several inflammatory-related genes, including cytokines, USP24-mediated IL-6 expression might be crucial to control the other cytokines in the tumor-associated microenvironment." (PMID 30266897, 2018). "However, while IL-6 deficiency ameliorates DEN-induced HCC in lean and obese mice, inactivation of IL-6 receptor alpha (IL-6Rα) reduces DEN-induced tumor burden only in lean mice, suggesting a compensatory overlapping signaling cascade in obese IL-6Rα-deficient mice." (PMID 30224299, 2018). "Moreover, chemerin knockout mice with accelerated tumor growth exhibited increased expression of granulocyte-macrophage colony-stimulating factor (GM-CSF) and IL-6 and accumulation of myeloid-derived suppressor cells (MDSCs) and tumor-associated macrophages (TAMs)." (PMID 30555465, 2018). "We found that loss of IL-6 resulted in reduced levels of multiple serum cytokines and chemokines that are part of the JAK-STAT3 signalling pathway and a reduction in tumour incidence; and where there were sufficient tumours to analyse, mice with loss of IL-6 showed reduced spread to other organs." (PMID 29343721, 2018).
tumor (continued). "We expect that larger doses of TCZ may be necessary to achieve this same type of interference when xenografts include both human endothelial cells and human tumor cells, as in this case the amount of competing IL-6 in the tumor microenvironment will significantly increase." (PMID 29351275, 2018). "Sustained overproduction of IL-6 and STAT3 was found to contributes to arsenic causes carcinogenesis and STAT3 is also required for cellular transformation and performed pro-tumorigenic functions, including promotion of tumor cell proliferation, survival, invasion, metastasis, and angiogenesis." (PMID 30185897, 2018). "Interestingly, MDSCs are another source of IL-6 in the tumor niche." (PMID 30154786, 2018). "Thus, the literature supports the ability of RTK inhibitor-induced reprogramming through increased secretion of IL6 and TGFβ to enhance immune evasion such that combinations of RTK inhibitors and blockade of IL6 or TGFβ signaling allows participation of the immune response in tumor control." (PMID 29458371, 2018). "Thus, it is plausible and likely that the tumor stroma and immune microenvironment still contains Stat3 which may be functionally targeted by IL-6 blockade." (PMID 30389925, 2018). "Thus, targeting IL-6 may offer exciting therapeutic opportunities to reactivate macrophage-mediated tumor immunity, which may block tumor progression and treatment resistance." (PMID 29422647, 2018). "So far, tumor-promoting effects of adipocytes are linked to their secretion of adipokines, hormones, and growth factors including matrix metalloproteinase 11 (MMP11), IL-6, IL-1β into the surrounding TME, which collectively enhance the migration and invasion capacity of cancer cells." (PMID 28929459, 2018). "Detection of IL-6 in urines of same individuals was neither effective in predicting patients bearing PCa nor in identifying, among diagnosed PCa, those at risk of developing an aggressive tumor (data not shown)." (PMID 29896191, 2018). "IL6 was the most significantly upregulated gene within inflamed-irEC samples compared to matched controls; the majority were not upregulated in association with tumor-response to CPIs." (PMID 30400822, 2018). "4T1 tumours express high levels of Il6 mRNA, and the protein could be detected in the serum." (PMID 30054470, 2018). "One might speculate that our findings of an IL-6 dependent redistribution of immune cells to the tumor site might be a result of hyperthermia facilitated accessibility and the induction of IL-6 trans-signalling with subsequent IL-6 dependent on the upregulation of adhesion molecules." (PMID 30126117, 2018). "Having established that the FAP+ HO-1+ TAM phenotype was regulated by IL-6 signalling, we next considered whether these cells might also populate specific anatomical locations within the 4T1 tumour, and discovered a tendency for these cells to accumulate around viable vasculature." (PMID 30054470, 2018). "On day 21, granulocyte-colony stimulating factor (G-CSF), granulocyte-macrophage (GM)-CSF, IL-4, IL-6, and IL-10 were found to be increased by calcitriol and its analogs, whereas on day 33, their level was found to be decreased as compared with control tumor-bearing mice." (PMID 30037009, 2018). "Importantly, PNA3-pHLIP treatment lowers both tumor and blood levels of IL-6, suggesting that impacting the local (tumor) microenvironment may result in systemic (peripheral) effects, such as reducing inflammation." (PMID 28420874, 2017). "Moreover, G-CSF and IL-6 may promote expansion of myeloid derived suppressor cells, which can interfere with T cell activation and anti-tumor responses." (PMID 28827632, 2017). "However, this is purely speculative and more work is needed to clarify the role of IL-6 in NK cell homing to the tumor site." (PMID 28324125, 2017).
tumor (continued). "However, depletion of IL-6R did not completely abrogate the malignancy promotion conferred by MGDAs, indicating that an unknown pathway distinct from the IL-6R/IL-6 signalling mediates the promotion of tumour malignancy by adipocytes." (PMID 28281525, 2017). "Additionally, dual immunofluorescence staining for both Shh and IL-6 of diagnostic lymph node specimens further confirmed that the primary tumor microenvironment is not the only source of serum Shh and IL-6." (PMID 28496132, 2017). "In addition, recent reports indicated that IL-17 could induce tumor cells to secrete IL-6 and promote tumor growth by STAT3 pathway." (PMID 28002798, 2017). "Cytokine profiling of the primary tumour identified human IL-6 and TNF-α – consistent with the corresponding murine factors found in the mouse tissue, and indicative of pro-inflammatory response – but also a range of other factors that could be derived from both innate and adaptive immune cells." (PMID 28417956, 2017). "In this study, we examined if BZA could mediate its anti-tumor effects by blocking IL-6 signaling." (PMID 28978005, 2017). "Therefore, the elevated IL-6 levels secreted by T cells in patients 10 and 14 might indicate successful targeting of tumor cells." (PMID 29268708, 2017). "An increase of IL-6 in the tumor could be observed after the fifth fraction of radiation." (PMID 27664151, 2017). "In addition, HBEGF and IL6 can promote tumor growth/invasion acting on tumor cells." (PMID 28977919, 2017). "Besides, IL-6 production from tumor cells and other inflammatory cells influence each other." (PMID 28088791, 2017). "However, no further examination of IL6 as a potential testis-tumor promoting factor or its underlying signaling pathways has been conducted." (PMID 29250030, 2017). "Interestingly, IL6 was found at higher concentrations only in the orthotopic tumor-bearing group." (PMID 27901481, 2017). "In this study, the reasons for the association with serum CRP levels and the efficacy of nivolumab remain unclear, but serum CRP and IL-6 levels have previously been shown to predict tumor response and survival to immunotherapy, such as high dose IL-2, IFN alpha, and ipilimumab." (PMID 29262550, 2017). "Whole-genome transcriptome profiling, in vitro and animal experiments revealed that interleukin 6, interleukin 8, chemokine (C-X-C motif) ligand 1, galectin-1, and selected proteins of the extracellular matrix (e.g., fibronectin) do have similar regulation during wound healing and tumor growth." (PMID 29072623, 2017). "GM-CSF and M-CSF along with other cytokines like IL-6 and IL-8 have been shown to be involved in recruitment and differentiation of myeloid cells into M2 macrophages and myeloid derived suppressor cells (MDSCs) in the tumor apart from promoting tumor angiogenesis." (PMID 28750018, 2017). "IL-6 could be secreted by many inflammatory cells as well as tumor cells." (PMID 28088791, 2017). "On the basis of definite anti-tumor efficacy of Bazedoxifene and its safety, Bazedoxifene may be extended application to investigate its inhibitory effect on other cancer types that persistent express IL-6/GP130 signaling." (PMID 28672024, 2017). "In addition, elevation of circulating TNFα and IL-6 in LLC tumor-bearing mice is dependent on TLR4." (PMID 28536426, 2017). "However, the binding of TNFSF15 to its receptor, TNFRSF25, amplifies the expression of IL-4, IL-6, GM-CSF, and IL-1758,59, which may explain the overactivity of these tumour-promoting cytokines in our network." (PMID 29062084, 2017). "Moreover, we showed that tumor inhibitory effect of GMI was via IL-6/Stat3 signaling pathway." (PMID 29050290, 2017). "In addition, IL-6 promotes tumor proliferation through the activation of the Ras/Raf/MEK pathway." (PMID 29212288, 2017). "In addition to IL-6, the increase of IL-35 expression in tumor could increase IL-17A and G-CSF in blood and tumor microenvironment." (PMID 28432279, 2017).
tumor (continued). "In addition, by releasing proinflammatory cytokines, such as tumor necrosis factor-alpha (TNF-α), interleukin (IL)-6, and vascular endothelial growth factor (VEGF), tumor cells and tumor-associated leukocytes play a direct role in promoting proliferation and metastasis." (PMID 28358923, 2017). "In this process, MSCs might secrete someanti-tumor cytokines such as interleukin-6 and -8." (PMID 28367423, 2017). "We first cleared IL-6 using an IL-6 specific monoclonal antibody (mAb) which led to a diminished tumor control and also a less pronounced immune cell infiltration to the tumor; however, we could not mimic the role of IL-6 by administration of recombinant cytokine." (PMID 28324125, 2017). "Therefore, inside of the tumor cells, IL-37 might suppress some factors which contribute to tumor development, such IL-6 or β-catenin we discussed here." (PMID 28467774, 2017). "Thus, increasing the overall levels of IL-6 in the tumor microenvironment by adding ADSCs might have promalignant consequences in vivo." (PMID 28545495, 2017). "This increase may have caused increased IL-6 expression and secretion, which in turn leads to activation of STAT3 and a subsequent upregulation of downstream targets that promote tumorigenesis and tumor cell proliferation." (PMID 28350804, 2017). "In addition, ID proteins are implicated in tumor angiogenesis and induce expression of pro-angiogenic factors including hypoxia-inducible factor-1α (HIF1α), vascular endothelial growth factor A (VEGFA), interleukin-6 (IL-6)." (PMID 28881649, 2017). "Therefore, we hypothesized that targeting of IL-6 signaling could reverse the resistant phenotype in tumor cells, thereby enhancing the anti-tumor effects of cisplatin and radiation treatment in HNSCC." (PMID 28978005, 2017). "Thus, influencing factors such as COX2 and IL-6 display effects on tumor progression." (PMID 28402937, 2017). "Thus, we investigated whether BRD2 contributed to the transcriptional regulation of pro-cachectic factors such as IL6 or PTHrP in the tumor." (PMID 29167426, 2017). "Mechanically, CTC-derived ligands for TLR2 and TLR4 (TLR2/4) induced the systemic inflammation, thus increasing the production of proinflammatory cytokines such as G-CSF and IL-6 that could induce the conversion of neutrophil function from tumor-suppressing to tumor-promoting." (PMID 28415700, 2017). "Moreover, serum IL-6 produced by tumor cells could increase the drug resistance to chemotherapy, which may also contribute to tumor recurrence after surgery." (PMID 28977974, 2017). "However, we believe that the measurement of IL-6 levels may be a useful method of recognizing patients who are at greater risk of STS and tumor-related death." (PMID 28851899, 2017). "It will be important to investigate whether Oligo-Fucoidan impacts the classical activation of M1 macrophages and/or the inhibition of M2 macrophages via inhibiting CCL2 and IL-6 signaling, which modulate anti-inflammation, tumor immunity and tissue remodeling (angiogenesis and metastasis)." (PMID 28928376, 2017). "Together, these data suggest that enriched IL-6 expression in the prostate can amplify the inflammatory responses in the local tissue and peri-prostatic adipose tissue, which may confer as one of the pathways to induce neoplasm in the prostate." (PMID 28077171, 2017). "Global increase of hepatic interleukin-1β, interleukin-6, tumor necrosis factor-α and hepatocyte growth factor was detected in low-fat/high-carbohydrate and high-fat with respect to standard diet fed mice as well as in tumor with respect to non-tumor bearing mice." (PMID 28881825, 2017). "We then investigated whether IL-6-treated tumor cells showed increased migration and invasion." (PMID 28846080, 2017).